MIR1323 (microRNA 1323)
Synonyms: hsa-mir-1323; MIRN1323; mir-1323
Gene: MicroRNA gene on chromosome 19 (53,671,968 to 53,672,040, forward strand). Ensembl gene ENSG00000221017.
Homologues: Orthologues: chimpanzee ptr-mir-1323 (100% identical).